TNF (tumor necrosis factor)
Diseases named in the same sentence as TNF in open-access papers (continued):
Sharing a sentence is not in itself a finding about the gene and the disease.
tumor (continued). "The activation of the TLR4 signaling pathway induces TNF-α and NF-κB, leading to the promotion of CRC; TNF-α knockout mice treated with AOM/DSS show significantly less tumor formation, representing the pro-tumorigenic role of TNF-α." (PMID 25076949, 2014). "When expressed locally by immune cells, TNF-α has a therapeutic role in destroying tumor blood vessels and inducing the apoptosis and necrosis of tumor cells." (PMID 25010932, 2014). "Picogram amounts of TNF-α are constitutively secreted by many tumor types, and appear to stimulate cancer growth, although the underlying signaling mechanisms are not completely understood." (PMID 24672527, 2014). "Studies have demonstrated that TNF-α is a key cytokine amongst all cytokines of the tumor microenvironment." (PMID 24676340, 2014). "Several extrinsic factors previously reported to be associated with the tumor microenvironment were identified, including GCSF, THBS1, S100A8/A9, CCL2, TNF and TNFSF11." (PMID 25593989, 2014). "IL-1 mediates cytotoxicity and suppression of tumour growth and TNF-α inhibits angiogenesis to prevent tumour growth." (PMID 26316944, 2014). "Our data showed that protumor neutrophils can be remodeled by IFN-γ and TNF-α, even in the presence of G-CSF/IL-6, resulting in the conversion of neutrophil function from tumor-promoting to tumor-suppressing." (PMID 25587026, 2014). "It is important to note that the group of mice that received TNFα/MAGE-AX/GK-1 BMCDs retained the lowest rate of tumor growth since the beginning of the treatment." (PMID 25759825, 2014). "Generally, the increases of iNOS activities related to the proinflammatory agents - endotoxin, IL-1β, TNF-α and interferon-γ can be induced shock and over inflammatory responses in the body, and over expressions of iNOS also induced tumor neovascularization." (PMID 25477992, 2014). "Mast cells will also release TNFα, known to help deliver oxygen to hypoxic areas of the tumor allowing for tumor growth, and release CXCL2, seen to induce melanoma cell proliferation." (PMID 24949488, 2014). "An experimental animal tumor model has shown that anti-TNF-α antibodies hinder the innate anti-tumor immune responses and promote the growth of immunogenic rat colon tumors that are rejected by immunocompetent untreated rats." (PMID 25267341, 2014). "A decreased CD8+ T cell proliferation was detected upon co-cultivation of T cells with IL-4 pretreated as well as with IL-4 and TNFα pretreated tumor cells." (PMID 24885059, 2014). "Chronic TNFα expression in the tumor microenvironment is correlated with a more aggressive tumor phenotype." (PMID 25566498, 2014). "More comprehensive analysis of soluble factors will be required to determine how fibroblast-derived factors regulate the growth of tumor cells and how TNF alters the signaling between tumor cells and fibroblasts." (PMID 24818101, 2014). "Overproduction of HSP70 leads to increased resistance against apoptosis-inducing agents such as tumor necrosis factor-α and doxorubicin and can promote tumor growth and metastatic potential in rodent models." (PMID 25058392, 2014). "Key features of cancer-related inflammation include NF-κB activation: inflammatory cytokines such as TNFα and IL-Iβ activate NF-κB in both tumor and inflammatory cells, leading to the expression of several mediators." (PMID 24457902, 2014). "The tumor-killing effects of eosinophil-derived TNF were the first description of a cytokine, chemokine, or growth factor elaborated by eosinophils implicating a role for these immunomodulators in cancer." (PMID 25426119, 2014). "In mice inoculated by CellsRas-G12V+TNFαCMRas-G12V+TNFα, the lag period until dissemination of tumor cells to LN was shorter, and the percentage of mice with LN metastases was higher (83%) compared to all other Cell-CM combinations (12-36%)." (PMID 24598028, 2014).
tumor (continued). "Animal models have shown a positive relationship between TNF-α and tumor development and progression in liver and colorectal cancer with elevated circulating concentrations in different tumoral types." (PMID 24829560, 2014). "TNFα, a cytokine released into the TUMIC and linked to tumor progression, induces neutrophil degranulation and VEGF release and CXCL8, CXCL1 production, thus favoring angiogenesis." (PMID 25072019, 2014). "In a previous study, in an orthotopic mouse model of pancreatic cancer, treatment with anti-TNF-α antibody resulted the reduction of tumor growth and metastasis." (PMID 24676340, 2014). "In line with this, macrophage-specific SOCS3 knockout animals are resistant to tumor transplantation due to reduced secretion of tumor-promoting TNF-α and IL-6, together with elevated MCP2/CCL8 that is anti-tumorigenic." (PMID 25120543, 2014). "In our study on Helicobacter pylori (H. pylori) carcinogenesis, we discovered that tumor necrosis factor-α (TNF-α)-inducing protein (Tipα) of H. pylori is a carcinogenic factor that induces tumor promotion in vitro and in vivo." (PMID 24469254, 2014). "Real-time PCR array revealed a downregulated expression of the anti-apoptotic gene BCL2 in Spn4A-expressing tumor cells and an increased expression of the pro-apoptotic gene TNF." (PMID 24961901, 2014). "Tumor cell-derived TNF-α is a important factor produced by tumor cells and plays a key role in the tumor microenviroment." (PMID 24676340, 2014). "Fas ligand and TNFα reportedly kill not only tumor cells but also normal cells, whereas, TRAIL is promising because of its high selectively to cancer cells." (PMID 24297392, 2014). "Tumour necrosis factor-alpha (TNF-α) is a pro-inflammatory cytokine, primarily released by activated monocytes/macrophages as well as tumour cells." (PMID 26019577, 2014). "These include cytokines, chemokines and interleukins including interleukin 6 (IL-6), transforming growth factor-β (TGF-β), tumor necrosis factor-α (TNF-α), and interferon-γ (INF-γ), all of which are associated with chronic inflammation and tumor progression." (PMID 24523696, 2014). "Taken together, these results demonstrate that the response of protumor neutrophils to T-sMs was reversed by priming with IFN-γ and TNF-α, thus resulting in the conversion of neutrophil function from tumor-promotional to tumor-suppressing." (PMID 25587026, 2014). "Treatment with Ad-hLF increased the levels of serum interferon-γ, serum interleukin-2 (IL-2) and tumor necrosis factor-α, and decreased the levels of serum IL-4 in tumor-bearing mice." (PMID 24520300, 2014). "In the co-culture with HeLa cells, when tumor cells were pre-treated with the HO-1 inhibitor, TNF-α production was significant in NK-92 cells (p <0.05)." (PMID 25302050, 2014). "The tumor source of TNF-α can be derived from myeloid or tumor cells and through an autocrine activation can stimulate tumor growth and angiogenesis." (PMID 24901008, 2014). "Our current study observed that both Enbrel and low-dose TNF-α pretreatments before IR markedly reduced the mRNA expressions of tumor promoting factors, IL-6 MMP-9 and E-selectin in IR liver." (PMID 24397824, 2014). "TNF-α has been known to contribute to chronic inflammation and promote tumor formation, growth and metastasis." (PMID 25548907, 2014). "It is supposed that inhibition of tumor cell growth is the result of β-glucan-dependent stimulation of macrophages and dendritic cells followed by secretion of various cytokines including TNF-α, IFN-γ, and IL-1β, and stimulation of NK T and B cells." (PMID 25114920, 2014). "Comparison of CellsControlCMControl to CellsRas-G12V+TNFαCMControl (groups 1 vs. 3) has shown that expression of RasG12V in the cells (stimulated in vitro by TNFα prior to their injection to mice), has led to increased tumor growth." (PMID 24598028, 2014).
tumor (continued). "It is therefore important to find out how to selectively trigger the anti-tumor properties of TNF-α while avoiding or inhibiting its tumorigenic properties." (PMID 25419573, 2014). "They resembled effector memory αβT (TEM) cells and retained full functionality as assessed by in vitro tumor cell killing as well as secretion of pro-inflammatory cytokines (IFNγ, TNFα) and cell proliferation in response to stimulation with phosphoantigens." (PMID 25101086, 2014). "TNF-α induced activation of mitogen-activated protein kinases (MAPKs) are also significant factors for tumour growth." (PMID 24918094, 2014). "In the C3-B mouse model, the expression of the anticancer-associated cytokines (TNF-α, IFN-γ, IL-2, and IL-12) were measured by ELISA assay in the host spleen and the local tumor area." (PMID 25510204, 2014). "To explore the effect of TNF-α on IR-induced growth of colorectal liver metastases, we examined tumor growth in the excised livers." (PMID 24397824, 2014). "We demonstrated that TNF secreted by AML cells stimulates the survival/proliferation of tumor cells by inducing the activation of NF-κB and JNK, two parallel survival/proliferation signaling pathways." (PMID 25526629, 2014). "The anti-tumor effect of TNF-α and/or IFN-γ was augmented by neutrophil chemokine CXCL1, and was attenuated by depleting neutrophils." (PMID 25587026, 2014). "Corresponding to the in vitro experiments, TNF-alpha levels in tumour and liver tissue were heightened." (PMID 24895598, 2014). "Certain studies have found that TNF-α promotes a variety of inflammatory cytokines and chemokines, thus affecting the formation and development of tumor blood vessels, promoting tumor invasion and metastasis." (PMID 24676340, 2014). "There is also evidence that prolonged TNF-α exposure can enhance the proportion of cancer stem cell phenotypes in oral squamous cell carcinoma, increasing their tumor-forming sphere ability, stem cell-transcription factor expression, and tumorigenicity." (PMID 24901008, 2014). "Proinflammatory cytokines, i.e., IL-1β, TNF-α, IL-6 produced by tumor or host tissue due to tumor presence leads to both systemic and local inflammation in cancer." (PMID 25415607, 2014). "Studies have investigated the effects of TNF-α on tumor cell metastasis, demonstrating that TNF-α enhances the invasive capacity of cancer cells." (PMID 24676340, 2014). "The results indicate that CM derived from TNFα-stimulated WT-Ras-expressing tumor cells (shown to produce highly elevated levels of CXCL8) induced significantly stronger angiogenic effects compared to control cells." (PMID 24598028, 2014). "TNF-α is also produced by neoplastic cells or cells in the tumor microenvironment and can act as an endogenous tumor promoter." (PMID 25010932, 2014). "Inhibition of TNF-α elevation remarkably attenuated the increases of these liver inflammatory damage indicators and tumor-promoting factors." (PMID 24397824, 2014). "Activated glia can produce multiple cytokines, chemokines,and enzymes that lead to increased tumor invasion, including IL-1β and TNF-α, markers that were upregulatedin this study." (PMID 25129445, 2014). "Overall, experiments on HCC and many other tumor types have established that TNF-α is intimately involved in all aspects of cancer development, including transformation, proliferation, angiogenesis, invasion, and metastasis." (PMID 24672527, 2014). "Numerous studies have confirmed that tumor necrosis factor-α (TNF-α) is a key cytokine amongst all cytokines of the tumor microenvironment which promote tumor cell proliferation and invasion." (PMID 24676340, 2014). "A previous study has also demonstrated that the steroid saponin, diosgenin, inhibits tumor necrosis factor-induced NF-κB activation and blocks the proliferation of tumor cells." (PMID 25120710, 2014).
tumor (continued). "Astragalus membranaceus polysaccharide improves immune response in the host individual by inducing IL-2, IL-12, and TNF-α secretion, as well as inhibits tumor progression in vivo." (PMID 24969238, 2014). "A similar trend was found with MCP-1, a chemokine that has previously been shown to recruit IL-1- and TNF-α-secreting macrophages to sustain VEGF secretion by tumor cells in a proangiogenic signaling loop." (PMID 24698959, 2014). "We believe, this is a promising approach to induce tumor cell death and diminish tumor blood supply with an anticipated reduction in undesired toxicity that is seen with the use of exogenous TNF in the ILP treatment regimens." (PMID 24664144, 2014). "In parallel, we asked what is the impact of combined TNFα stimulation and Ras hyper-activation on tumor growth and metastasis." (PMID 24598028, 2014). "Consistent with these divergent effects on energy metabolism, TNFα levels in obese animals are higher than that in control rats but significantly lower than that in tumor-bearing rats." (PMID 25358444, 2014). "7.761 months; log rank test p = 0.00015) In conclusion, we can affirm that TNF-α affects tumour development along with disease progression which has an impact on the survival of CRC." (PMID 26019577, 2014). "A key determinant of adaptive immune priming following DC maturation is the profile of appropriate cytokines (including TNFα, IFNα, IL-12p70 and IFNɣ) secreted within the tumor microenvironment." (PMID 23982804, 2014). "It is tempting to further interpret this unexpected finding in terms of differential roles for TNF-α in different parts of the tumour." (PMID 24979620, 2014). "This fosters pro-death and anti-angiogenic signaling through the remaining cytotoxic TNFR1/p55, especially when apoptotic and necrotic tumor cells produce more TNF." (PMID 24664144, 2014). "The suppression of TNF-α function favours tumour proliferation and differentiation through the activation of IL-10." (PMID 26316944, 2014). "At later times, however, increase in TNF-induced apoptosis and accumulating necrotic mass slows down tumor growth predicting a balance of cell proliferation and cell death." (PMID 24664144, 2014). "The TNF-α protein induces the expression of adhesion molecules, facilitating the invasion of metastatic tumor cells, and high levels of endogenous TNF-α have been observed in the blood of some cancer patients." (PMID 25420786, 2014). "IGF-1 and TNF-α can activate tumor microenvironment and aid tumor cells in escaping from the primary tumor." (PMID 25203554, 2014). "Macrophages are activated by β-glucans and other cell mediators to kill tumor cells by the production of TNF-α and ILs." (PMID 24348858, 2014). "In this study we have shown that TNFα rescued the tumor-promoting potential of WT-Ras and have demonstrated cooperativity between TNFα and activated Ras in metastasis." (PMID 24598028, 2014). "TNF-α is a key cytokine, which plays a critical role in tumor immunity as well as in immunity against infection." (PMID 24868535, 2014). "IFN-γ activates macrophages for phagocytosis and lysis, and TNF-α promotes direct killing of tumor cells by NK cells." (PMID 24520300, 2014). "Jointly, TNFα + Ras activities have given rise to increased angiogenesis and to elevated tumor cell dissemination to lymph nodes." (PMID 24598028, 2014). "Previous studies indicate that TNF-α induces not only hyperpermeability of existing blood vessels but also tumor vasculogenesis." (PMID 24466321, 2014). "A set of pro-inflammatory cytokines consisting of TNF-α and IL-1 and 6 is essentially tumor directing." (PMID 24782866, 2014). "We also revealed the presence of paracrine loops between PRL-3 and TAMs, which function via TNF-α in the tumor microenvironment." (PMID 24885636, 2014).
tumor (continued). "IL-4 and TNFα can both be produced by different immune cells and thus represent components of the tumor microenvironment." (PMID 24885059, 2014). "The co-stimulation with IFN-γ and TNF-α was more efficient in promoting anti-tumor function of neutrophils." (PMID 25587026, 2014). "The necrotic population and growing TNF concentration reverse tumor growth and decrease tumor volume." (PMID 24664144, 2014). "Low doses of TNF promote tumor growth and progression while high doses of TNF have tumor inhibitory effects." (PMID 24664144, 2014). "Both HNSCC derived cell lines and invasive HNSCC tumor cells produce proinflammatory cytokines including IL-1β, TNF-α, and IL-6." (PMID 24465623, 2014). "On the other hand, low TNF-α levels increase tumor growth, induce angiogenesis of diverse tumors in mice, and induce a subpopulation of tumor-associated myeloid cells coexpressing endothelial and myeloid markers with proangiogenic/provasculogenic properties." (PMID 24901008, 2014). "IR treatment led to a significant increase in tumor growth; however, both Enbrel and low-dose TNF-α pretreatment tended to attenuate this increase." (PMID 24397824, 2014). "ICAM1 expression was highly upregulated upon combined IL-4 and TNFα treatment, which can support T cell/tumor interaction." (PMID 24885059, 2014). "In a mouse model of melanoma, the co-transplantation of B16 cells with IFN-γ and TNF-α-pretreated MSCs promoted tumor growth." (PMID 24502410, 2014). "The enhancement of T cell function we observed was dominated by a more than 2 fold change in the tumor peptide (gp10025-33) specific secretion of TNF ex vivo, mirroring the data observed in serum cytokine levels." (PMID 25054063, 2014). "Substantiating this observation, BCG rescued A549 xenografts from TNF-α-mediated tumor clearance in nude mice." (PMID 25208737, 2014). "All of these features clearly position TNF for inclusion in tumor targeting strategies, a strategy that has been pursued by various groups using scFv:TNF-based fusion proteins." (PMID 23840967, 2013). "Tumour necrosis factor-alpha (TNF-α) and nuclear factor of kappa light chain gene enhancer in activated B cells (NF-κB) play critical role in carcinogenesis processes like tumour initiation, proliferation, migration and invasion." (PMID 24324738, 2013). "Selective delivery of TNF to tumor vessels has been achieved by fusing this cytokine with a tumor-vasculature-homing peptide that contains the Cys-Asn-Gly-Arg-Cys (NGR) sequence, a ligand of a CD13 isoform expressed by neo-angiogenic vessels." (PMID 24062984, 2013). "In the region where the tumor mass is situated, only a few microglia express inducible nitric oxide synthase (iNOS) and tumor necrosis factor-alpha (TNF-α)." (PMID 23983766, 2013). "This in turn is potentially tumourigenic, and TNF can indeed promote tumour growth, proliferation of tumour cells, as well as angiogenesis, invasiveness and metastasis." (PMID 23852022, 2013). "It is known that NF-κB regulates the expression of several genes, such as COX-2, the matrix metalloproteinase MMP-9, iNOS, TNFα, IL-8, and other anti-apoptotic proteins, involved in tumor initiation, promotion and metastasis." (PMID 23529027, 2013). "A number of therapeutic approaches have been proposed to enhance the anti-tumor effect of suicide gene therapy by inducing an immune response to tumor cells via co-expression of cytokine genes, such as IL-2, IL-2 and TNF-α, IL-12, and IL-21." (PMID 23441198, 2013). "The BHE extract and its BuOH fraction expressively reduced the TNF-α level on the liver homogenates of tumour-bearing rats when compared to control, perhaps contributing to a recovery of the hepatic Cat activity in these animals." (PMID 23408945, 2013). "Studies have suggested that following STAT3 inhibition, the levels of TNF-α increase, promoting a more inflammatory macrophage/microglia resulting in inhibition of tumor growth." (PMID 24244348, 2013).